CD68 (CD68 molecule)
Diseases named in the same sentence as CD68 in open-access papers (continued):
Sharing a sentence is not in itself a finding about the gene and the disease.
tumor (continued). "Expression of CD68 (a pan-macrophage marker specific for human antigen) was found to be positive only in the patient tumor stroma and not in the subcutaneous PDX and PDOX, suggesting that the TAMs in PDX and PDOX may have been replaced by mouse macrophages." (PMID 31732509, 2019). "Similarly, we observed a moderate correlation (R = 0.67, P = 0.03) between macrophage (CD68+) populations and a strong correlation (R = 0.92, P < 0.001) between cells positive for vessel marker CD34 when comparing the larger tumor specimen and core biopsy." (PMID 31772388, 2019). "Moreover, CD8+ TIL and CD68+ TAM did not significantly correlate with tumor size (p = 0.260, p = 0.441), tumor differentiation (p = 0.858, p = 0.840), tumor depth (p = 0.158, p = 0.225) or TNM stage (p = 0.123, p = 0.561)." (PMID 31521128, 2019). "CD68+ macrophages were present in high quantities in both tumor and adjacent non-tumor tissues." (PMID 30283446, 2018). "Thus, we suggest that CD68+ polyP-expressing mast cells could crosstalk with neutrophils through polyP, leading to NET generation and their subsequent implication in tumor biology." (PMID 29543850, 2018). "We found CD68 macrophages strongly expressed B7-H1 protein and tumor cells were negative." (PMID 29695237, 2018). "However, recent immunochemistry studies have provided better evidences of the origin of this tumor which show positive for S-100 protein, neuron-specific enolase, and CD68 but negative for muscular markers such as myoglobin, keratin, and desmin." (PMID 27068886, 2018). "E-cadherin levels showed a correlation with high CD8 TN/STR (rank Spearman p=0.0435) and from this it was noted that those cells with low levels of E-cadherin had significantly lower numbers of CD8, FoxP3, and CD68 cells in the tumour nest but not in the stroma and hence lower TN/STR ratios." (PMID 29416729, 2018). "Looking at the other immune biomarkers, CD8 and to lesser extent CD68, most often showed pronounced infiltration on both sides of the tumor-nest-TME interface, as opposed to the other immune markers that tended to be more diffusely arranged in both compartments." (PMID 29874226, 2018). "However, CD56 and CD68 stainings were performed only for 40 patients due to lack of tumour material at the time of analysis." (PMID 29269742, 2017). "In addition, Mint3 expression in MEFs slightly increased the number of endothelial marker CD31-positive cells, but not that of the macrophage marker CD68-positive cells, in the tumours from co-injected MDA-MB-231 cells." (PMID 28504692, 2017). "In conclusion, our retrospective study comprising 89 CRC patients with stages IIA, IIIB, and IIIC confirms that infiltration of the tumor stroma by CD68+/iNOS− TAMs and CD8+/FoxP3+ Tregs is a negative prognostic factor and there is a positive correlation between these types of infiltration." (PMID 28343267, 2017). "CD68+ cells were observed in the tumor mass of both non-irradiated and irradiated mice." (PMID 29069812, 2017). "Although our group recently reported prognostic importance of CD68 expression in PCNSL microenvironment, the major limitation was regarding therapeutic implication as it is difficult to modulate immune response via CD68 positive macrophages in PCNSL tumor microenvironment." (PMID 29152083, 2017). "While CD206+ cells represented about 12.0 ± 2.4 % of the CD68+ cells in the non-irradiated group, it significantly increased to 50.7 ± 5.3% and 49.9 ± 6.1 % in the tumor mass early and late after radiation, respectively, without any change in the absolute number of M2 MΦ." (PMID 29069812, 2017). "However, no significant increase in CD68+ macrophages in tumor tissue was observed under RG7356 treatment." (PMID 27507056, 2016). "The relationship between CD68+ TAMs and tumor prognosis is not clear-cut." (PMID 26938527, 2016).
tumor (continued). "With regard to the correlation of CA9, CD31, total CD68 and total CD20 expression with the clinicopathological parameters, patients younger than 65 years of age (median cut-off) had significantly lower percentages of tumor hypoxia and vice versa (low CA9 vs high: p < 0.001)." (PMID 27637082, 2016). "Interestingly, the increase of CD68-positive macrophages in the nest but not stroma correlates with the tumor location (P = 0.034) and mortality (P = 0.005)." (PMID 26769084, 2016). "An anti‐CD68 antibody was employed to assess TAMs and TAMIA expression, an anti‐CD34 antibody was utilized to detect MVD and EA expression, whereas an anti‐VEGF‐A antibody was used to detect CCP‐VEGF‐A; then, tumour sections were evaluated by image analysis methods." (PMID 27105577, 2016). "Because CD68 marker does not distinguish between M1 and M2 subpopulation and not all TAMs exhibit M2 phenotype, some TAMs show their M1 phenotype tumouricidal behaviour and inhibit tumour growth, and they can also be stained by CD68." (PMID 26843477, 2016). "We found elevated serum concentrations of HSP 27 and 70 in patients with TETs and strong expression of HSP27 and 70 in macrophages of the tumor microenvironment contrasting the finding of only few CD68/HSP70 double positive cells in fetal and adult non-neoplastic specimens." (PMID 27097982, 2016). "Furthermore, most of the CD68+CD206+ M2Mφs co-expressed CD11b antigen, indicating that recruited CD11b+ cells induced by irradiation are polarized into M2Mφs, resulting in contributions to tumour progression." (PMID 27271009, 2016). "Consequently, CD68+ tumour cells represent a ‘negative’ regulatory mechanism that blunts or limits immune responses in necrotic/progressive foci." (PMID 27304187, 2016). "Macrophage labelling with CD68 specific antibodies does not necessarily allow to discriminate macrophages from tumor cells since both cell types may present with positive staining patterns." (PMID 25807228, 2015). "This could explain why the decrease in CD3 (T-cells) and CD2 (T-cells, B-cells, NK cells) was more pronounced than that of CD8α (cytotoxic T-cells, NK cells, subset of DC), CD68 (macrophages, neutrophils, DC, myeloid progenitors), and CD163 (pro-tumor macrophages, M2)." (PMID 26374556, 2015). "Vimentin and CD68 staining in the stromal compartments of CRCs with low and high expression of TLR4 confirmed that the increased TLR4 signal was localized to PCMs and not related to tumor-associated macrophages." (PMID 24887394, 2014). "By IHC staining her tumor was CD1a, CD68, and S-100 positive and negative for CD30." (PMID 25405526, 2014). "Furthermore, sorafenib did not inhibit tumor recruitment of macrophages (CD68 and F4/80 markers), Fas, and lysozymes 1 and 2, which are important for macrophage anti-tumor activity." (PMID 24965046, 2014). "Consistently, we also found more infiltrating CD68-positive macrophages in PCa as compared to benign prostate tissues and there were no age differences between these two groups, suggesting a potential positive correlation of macrophages and CCL2 expression in human PCa tissues." (PMID 23982944, 2013). "Diagnosis of metastatic renal cell carcinoma (RCC) was confirmed by immunohistochemical stains, which showed the tumor cells to be positive for CD10, vimentin and pancytokeratin, but negative for CK7, carcinoembryonic antigen (CEA), chromogranin, synaptophysin and CD68." (PMID 23305230, 2013). "Notably, we did observe differences between genotypes in the Ki67 signal from CD68 negative cells, which are mostly tumor cells (CD68−/Ki67+: 49±5.7% in control versus 30.6±3.3 in Mφ-c-Myc-KO)." (PMID 23028984, 2012). "On the other hand, TIMP-2 score values at the tumor center correlated inversely with CD3 (r = −0.23, p = 0.021) or with CD20 (r = −0.21, p = 0.036) count in the invasive front, but correlated directly with CD68/(CD3+CD20) ratio in this same tumor location (r = 0.24, p = 0.014)." (PMID 23300781, 2012).
tumor (continued). "However, to verify that the co-cultivated fluorescent tumor cells were not contaminated with macrophages, we stained these cells for CD68, a macrophage marker." (PMID 21939504, 2011). "In fact, by immunohistochemistry we could measure weak CD68 staining in the host, peritumor and tumor tissues examined (not shown)." (PMID 21489226, 2011). "Furthermore, CD68 does not distinguish between macrophages polarized towards the pro-inflammatory (M1) or tumor-promoting (M2) phenotypes." (PMID 19641607, 2009). "In all patients, high tumour grade was positively associated with negative hormonal receptor status (P<0.001), high Ki-67 labelling index (P<0.001) and high expression of CD34+ (P<0.01), CD68+ (P<0.05), CD4+ (P<0.05) and CD8+ (P<0.05) T lymphocytes." (PMID 18797461, 2008). "The cell division marker Ki67 was positive in tumor cells and negative in histiocytes and osteoclasts; Stains for common leukocyte antigen (CD45) and for the histiocytic marker CD68 were positive in histiocytes and osteoclasts, but were negative in tumor cells." (PMID 17359524, 2007). "The predominant spindle cells of our tumor were negative for CD68." (PMID 18081931, 2007). "Interestingly, our models also stain positive for CD68, which is often implemented as a marker for infiltrating macrophages but which has also been identified in lymphoid cells, nonhematopoietic cells, mesenchymal stem cells and tumor cells." (PMID 41310103, 2025). "Interestingly, we observed an enrichment of CD68+CD206+ macrophages in vessel regions in several samples, suggesting that CD206-specific macrophages may promote tumor vascularization in a spatially dependent manner during tumor progression." (PMID 37723144, 2023). "Moreover, considering the relationship of TME, our findings showed that CD155 expression was positively correlated with the infiltration of CD68+ macrophages in TME and that combination of CD155 expression and levels of tumor-infiltrating T or B cells could predict the prognosis in GAC patients." (PMID 37441080, 2023). "Finally, triple-stained CD68/phospho-STAT1/c-Maf cells should have been examined in each case, as results may have enabled evaluation of the role of infiltrating M1 and M2 within the tumor." (PMID 37280312, 2023). "Therefore, we speculate that the PD-L1+CD68+ TAMs, but not the PD-L1+ tumor cells, are located near the specific CD8+ T cell subsets that exert suppressive effects." (PMID 36900182, 2023). "Therefore, high-infiltration with CD68+ TAMs was not correlated with tumor progression." (PMID 36693070, 2023). "Finally, all OSGC within each case displayed CD68 expression and partially a monocytes’ miRNA signature, suggesting that OSGC might be resident elements of TIME and likely belong to the spectrum of immunosuppressive, tumor-promoting, M2 TAMs." (PMID 36090031, 2022). "Additionally, fluorescent signal from the conjugated Cy5.5 was detected in some CD45-and CD68-expressing immune cells, indicating that Gd-Cy5.5-PhMV-mPEG/DGEA could be delivered by immune cells to the tumor region, resulting in a prolonged signal in the tumor." (PMID 36714624, 2022). "In addition, the positive signals of CD4+ T cells, macrophages (CD68+) and M2 macrophages (CD163+) were located in the microenvironment of the tumor invasion front, while CD8+ T cells were distributed not only in the microenvironment of the tumor invasion front but also within the tumor glands." (PMID 33818637, 2021). "In the current study, there is a high immune response illustrated by high expression of CD8, FOXP3 and CD68, which play an important role in tumour microenvironment and immune response, to ISG15 protein expression which may also support the role of ISG15 in controlling tumour microenvironment in BC." (PMID 33073304, 2021).
tumor (continued). "Common immunohistochemical markers (Iba1, HLA-DR, Cd68, F4/80) detect all brain macrophages and have not been particularly effective in distinguishing resident microglia from BAMs and monocytes/macrophages invading human tumor tissues under pathological conditions." (PMID 32194848, 2020). "Therefore, whether these cells may indeed be tumor-associated macrophages came into question and double staining for RPS27 was thus performed in conjunction with the macrophage marker CD68 on the same slide, confirming the presence of RPS27-positive macrophages within the tumor." (PMID 32349320, 2020). "However, to analyse if the presence of CTCs in general could be correlated with the amount of tumour-infiltrating T cells and intratumoural microglia, we immunohistochemically stained the tumours of the previously published cohort for CD3, CD8 and CD68 (n = 116)." (PMID 32151286, 2020). "However, CD68+PD-L1+ cell presence could reflect a feedback mechanism to restrict T cell responses through PD-L1 attenuation of CD8+ T cells and thus might reflect a beneficial local anti-tumour response." (PMID 28122336, 2017). "Notably, we did not observe the expression of CD68, CD204 and CD206 on CD14+HLA-DR−/low MDSC from OC, making them distinguishable from tumor-associated macrophages (TAM) with alternative polarization (M2) which has been well characterized and described to be correlated with RFS of OC patients." (PMID 29100353, 2017). "Indeed, there were more CD68-positive interstitial cells than IDO1-positive interstitial cells in RCC tissues, but virtually all the IDO1-positive interstitial cells localized to CD68+ areas, suggesting that IDO1 is present in inflammatory cells as well as in tumor and endothelial cells." (PMID 27572319, 2016). "CD68 staining analysed alone correlated to clinical characteristics for more aggressive tumors (e.g., higher T and N status) and an unfavourable prognosis, whereas HLA-DR staining in stromal cells had no impact on patients’ outcome or tumor characteristics (data not shown)." (PMID 26305673, 2015). "For example, CD4+ T cells, undefined CD45+, CD8+ T cells, and M0 macrophages CD68+ were much more abundant in the collagen-rich area of AGCT-1 in comparison with AGCT-2, whereas immune cell composition within the tumor area was not significantly different." (PMID 41042551, 2025). "The number of macrophages (CD68) and all TILs (CD45) were similar irrespective of the FGF2 status in the tumor samples." (PMID 40425576, 2025). "Immunohistochemical analysis demonstrated positive expression of CK, vimentin, and CD34 in tumor cells, with negative immunoreactivity for INSM1, S100, and CD68—findings consistent with the established pathological diagnostic criteria for ES." (PMID 41244767, 2025). "Since UPS and MFS cancer cells are known to express myeloid markers like CD68 and CD163, we reviewed the imaging data to ensure that the observed myeloid cell counts were not confounded by tumor cells expressing these markers." (PMID 40601026, 2025). "Regardless of CDK2AP1 status, CD68+ macrophages were mainly distributed in the periphery (P = .02), whereas CD3+ lymphocytes were primarily found infiltrating the tumor core (P = .009), as were monocytes (CD14+; P = .015)." (PMID 40112045, 2025). "We noticed that in all three cases, nearly all macrophages displayed CD68+/CD163+ M2-like phenotype and no VSIG4 co-expression with CD19+ tumor cells or CD31+ endothelial cells." (PMID 40539047, 2025). "In contrast, we found no disparities in the expression of the markers CD68, CD163, and CD86 within the tumor nest across the entire cohort." (PMID 40510346, 2025). "Immunohistochemistry showed that the tumor cells were positive for Vimentin, MDM, SMA, Bcl-2, Ki67, and CD99 and negative for TLE1, S-100, STAT6, CD34, ALK, CK-Pan, CD68, and ERG." (PMID 38287440, 2024).
tumor (continued). "The AFX test result was negative for both AE1/AE3 and CAM5.2 and positive for both CD68 and CD163, indicating that it was a nonepithelial tumor with histiocytic traits." (PMID 39171331, 2024). "High detection of PD-1 in immune cells infiltrating tumor epithelial islands correlated with the presence of high expression of CD8+ CTL (p=0.003), but not with CD4+ TH and CD68+ cells (p=0.604 and p=0.907, respectively)." (PMID 39035008, 2024). "Immunohistochemical staining of nude mouse subcutaneous tumor model of SOX2, CD44, CHI3L1, and CD24 in vivo shows the same result, and IHC staining of TAM markers CD68 had no obvious change." (PMID 39619148, 2024). "Next, we analyzed the presence of CD68 and CD163 (expressed by monocytes and Kupffer cells) and CD56 (expressed by NK cells) within the tumor and the surrounding nontumorous tissue." (PMID 38611048, 2024). "Markers for M2 macrophages, including CD68, CD163, and CD206, were found to be higher in lung tumor tissues compared to adjacent non-tumor lung tissues, regardless of histological types, including AC and SCC." (PMID 38791954, 2024). "Immunohistochemistry showed that the tumor cells were positive for Desmin and β-catenin but negative for Actin, S-100, EMA, ALK, CD68, Dog-1, and CD117." (PMID 38287440, 2024). "When TILs in tumours that received neoadjuvant chemotherapy (NACT) were compared to those that did not, the only significant results were seen in CD68." (PMID 38674108, 2024). "As biliary dysplasia progresses to an invasive state, CD68 + and CD163 + macrophage infiltration increases in the tumor mesenchyme rather than the epithelium, indicating temporal heterogeneity in immune cell distribution within the TMEs from different origins." (PMID 39068459, 2024). "The tumour cells express SMA and vimentin; partially express desmin, CD34, CD68 and ALK; and do not express CK or S100." (PMID 36855132, 2023). "Based on this result, to examine the pattern of distribution of CD8+ cytotoxic T cells and CD68+ macrophages/microglia in the tumor microenvironment of responders and non-responders, a CD8+ and CD68+ cell density map was generated." (PMID 36694264, 2023). "IMC analysis also revealed a trend towards reduction of M2 macrophages following treatment (F4/80+ CD206+ or CD68+ CD206+) and the trend was more pronounced in viable tumor compared with necrotic margin, but the difference was not significant." (PMID 37553182, 2023). "Subsequently, pathological biopsy of the lymph nodes revealed high expression of CD163, CD68, S100, Lys and CD34 in the tumor cells and no expression of CD1a and CD207, confirming this rare clinical diagnosis." (PMID 36969238, 2023). "There were significant positive correlations between microglia/macrophage markers CD68 (phagocytic)/triggering receptor expressed on myeloid cells 2 (anti-inflammatory) and CD8+ T cells in the invasive margins but not in the tumour core (P < 0.01)." (PMID 37324244, 2023). "Spatially, we observed elevated localization of CD68+ macrophages in the periphery of both HRD-Dup and FBI adnexal samples that extended into the tumour for HRD-Dup, but not FBI, samples." (PMID 36517593, 2022). "Our study found that sTILS, CD45+, CD3+, CD4+, and CD8+ cells tended to have a higher frequency in tumor tissue (stromal) and that the frequencies of CD20+, FoxP3+ and CD68+ cells in tumor tissue did not change after-NAT compared with before-NAT." (PMID 35562400, 2022). "As expected, CD8 positivity was significantly higher in DDIR-positive than negative tumours (median CD8 positivity 12.3% vs 6.24%, P = 0.037), as was CD68 positivity (median 4.33% vs 0.955%, P = 0.029)." (PMID 34728791, 2022).